TNFRSF13B (TNF receptor superfamily member 13B)
Diseases named in the same sentence as TNFRSF13B in open-access papers (continued):
Sharing a sentence is not in itself a finding about the gene and the disease.
TNFRSF13B also shares sentences with these, for which no sentence is quoted: multiple myeloma (15 papers); atherosclerosis (6); B cell lymphoma (6); Splenomegaly (6); leukemia (5); lupus nephritis (5); malaria (5); rheumatoid arthritis (5); hematological malignancies (4); Arthritis (3); bronchiectasis (3); glioma (3); Respiratory tract infection (3); allergic disease (2); central nervous system lymphoma (2); colitis (2); complication (2); genetic disorders (2); IgA nephropathy (2); lung carcinoma (2); Lymphadenopathy (2); mantle cell lymphoma (2); myositis (2); nephritis (2); pneumonia (2); respiratory infections (2); Waldenström’s macroglobulinemia (2); acute GVHD (1); Allergy (1); antiphospholipid syndrome (1).
A further 71 diseases each share a sentence with TNFRSF13B in 1 paper.